ENSG00000276216 (novel transcript)
Gene: Long non-coding RNA gene on chromosome 1 (145,281,115 to 145,291,294, forward strand). Ensembl gene ENSG00000276216.
Gene Ontology:
Molecular function: pre-mRNA 5'-splice site binding; triplet codon-amino acid adaptor activity
Biological process: mRNA 5'-splice site recognition; translation
Cellular component: U1 snRNP